CHD7 (chromodomain helicase DNA binding protein 7)
Diseases named in the same sentence as CHD7 in open-access papers (continued):
Sharing a sentence is not in itself a finding about the gene and the disease.
CHARGE syndrome (continued). "Xenopus, Drosophila, zebrafish, and mouse models have been established to further study the development and mechanism of CHD7 and CHARGE syndrome." (PMID 36172288, 2022). "Several mouse models have been established to better understand the role of CHD7 in CHARGE syndrome, especially given the wide range of congenital abnormalities that can occur." (PMID 36232804, 2022). "An area of focus for CHD7 research has been its role in neural crest cells, which contribute to many of the structures affected in CHARGE syndrome." (PMID 36172288, 2022). "As CHD7 is often mutant in CHARGE syndrome, we compared the locations of the mutations identified in CRC and CHARGE syndrome." (PMID 35789070, 2022). "To recapitulate the phenotypic manifestation of CHARGE syndrome in inner ear organoids, we next created mono- and bi-allelic CHD7 KO hESC lines by targeting the first of the 38 coding exons of CHD7 with CRISPR." (PMID 36396635, 2022). "The following sections will focus on the ocular complications of CHARGE syndrome and the role that CHD7 plays in the development of the eye." (PMID 36172288, 2022). "Previous research on CHD7 has focused on CHARGE syndrome and embryonic development, and little is known about its role in tumourigenesis." (PMID 35789070, 2022). "The wide spectrum of phenotypes observed in CHARGE syndrome is not only a result of the broad expression of CHD7 in development but also the wide range of potential downstream targets of CHD7 transcriptional regulation." (PMID 36172288, 2022). "We report, here, an extensive characterization of two mouse models of CHARGE syndrome, namely Chd7+/tm2a and Chd7+/Whi, encompassing metabolic, behavioural, immunological and morphological parameters." (PMID 36232804, 2022). "Chd7 mutants having shorter stature from birth fits with the reported ~65% of patients with CHARGE syndrome exhibiting this phenotype." (PMID 36232804, 2022). "This holds true for animal models, as seen in the diversity of inner ear phenotypes found in Chd7 mutant mice used to study CHARGE syndrome." (PMID 34589045, 2021). "The inner ear is particularly sensitive to CHD7 levels and is the most commonly affected organ in individuals with CHARGE syndrome." (PMID 34639189, 2021). "At present, there are two animal models commonly used to study CHARGE syndrome, Chd7 mutant mice and Chd7 mutant zebrafish." (PMID 34589045, 2021). "CHD7 mutations have been implicated in CHARGE syndrome; approximately 60–65% of patients with CHARGE have a mutation in CHD7." (PMID 33987750, 2021). "Children with CHARGE syndrome frequently exhibit autistic-like deficits in vocalization, social responsiveness, and repetitive behaviors, suggesting that CHD7 has a direct impact on autism." (PMID 33948885, 2021). "Missense CHD7 variants are more common in CHH patients, whereas null variants (e.g., nonsense, frameshift) are more common in CHARGE syndrome." (PMID 35047002, 2021). "Disease-causing variants in CHD7 and CHD8 cause CHARGE syndrome and a syndromic form of autism spectrum disorder, respectively." (PMID 33944996, 2021). "Genome distribution analysis revealed that CHD7 is predominantly located at active enhancer elements as it overlaps with p300, H3K27ac, and H3K4me1 occupancy, and CHD7-bound genes enriched neurulation pathway, consistent with CHARGE syndrome features." (PMID 33869187, 2021). "Collectively, our findings define epigenomic regulation by CHD7 in granule cell precursors and identify abnormal cerebellar patterning upon CHD7 depletion, with potential implications for our understanding of CHARGE syndrome." (PMID 34588434, 2021). "At this same residue of CHD7 Bergman and colleagues identified in a patient also with CHARGE syndrome a tyrosine (p.Cys1101Tyr), an amino acid with similar properties to phenylalanine." (PMID 34828433, 2021).
CHARGE syndrome (continued). "Accordingly, we have discovered that conditional CHD7 knockout triggers a striking cerebellar polymicrogyria phenotype, which we have also found in a case of CHARGE syndrome." (PMID 34588434, 2021). "The first prenatal NGS-diagnosis was performed via WGS on a fetus with multiple anomalies and a de novo translocation, disrupting CHD7, resulting in CHARGE syndrome." (PMID 33540854, 2021). "The test showed a mutation in chromodomain helicase DNA binding protein 7 (CHD7) gene, which, along with clinical features, allowed to establish a diagnosis of Charge syndrome." (PMID 34833458, 2021). "Chd7 knockout mice embryos cannot survive over embryonic day 10.5, but heterozygous mice show several similar defects observed in CHARGE syndrome." (PMID 34616726, 2021). "Studies conducted on mice showed that mutations in CHD7, a gene mutated in human CHARGE syndrome, lead to cochlear hypoplasia, while humans with CHARGE syndrome frequently present different anterior and posterior labyrinth anomalies." (PMID 34698066, 2021). "In the zebrafish chd7 mutant that models CHARGE syndrome, sema3e knockdown resulted in severe craniofacial malformations, including small eyes, defective cartilage, and an abnormal number of otoliths." (PMID 33869187, 2021). "Accordingly, conditional knockout of CHD7 triggers a striking phenotype of cerebellar polymicrogyria, which we have also found in a case of CHARGE syndrome." (PMID 34588434, 2021). "The PUF60 gene, as well as CHD7, is considered responsible for CHARGE syndrome, which cooperatively translocates nucleosomes to permit transcription of FGF8 by RNA pol II in neural development." (PMID 32071290, 2020). "Such prolonged transit times and longer dwell times in anterior DT in shank3abΔC+/− larvae are consistent with reflux and vomiting in individuals with PMS and phenotypes reported in a zebrafish chd7 mutant model of CHARGE syndrome." (PMID 30733854, 2019). "All this indicates that CHARGE syndrome is a highly heterogeneous disease and CHD7 gene analysis is important for comprehensive assessment." (PMID 31146700, 2019). "The Bergmann criteria focuses on patients with suspected features of CHARGE syndrome with CHD7 analysis." (PMID 31146700, 2019). "The broad spectrum of CHARGE syndrome symptoms is related to the regulatory function of CHD7 in the multipotent migratory neural crest in the embryonic period." (PMID 31146700, 2019). "So, in 2011, they emphasized that CHD7 analysis is helpful in the CHARGE syndrome diagnosis process and proposed a guideline for CHD7 analysis." (PMID 31146700, 2019). "While xenopus, drosophila, and zebrafish models have been established, mouse model is currently the predominant animal model for functional study of CHD7 and CHARGE syndrome." (PMID 29033785, 2017). "The altered cerebellar foliation pattern in Chd7 haploinsufficient mice show some similarities to those reported in mice with altered Engrailed, Fgf8 or Zic1 gene expression and we propose that mutations or polymorphisms in these genes may modify the cerebellar phenotype in CHARGE syndrome." (PMID 29168327, 2017). "Studies of CHD7 in the CHARGE syndrome not only highlight the critical role of CHD7 in development but also indicate that CHD7 modulates central pathways in tumorigenesis." (PMID 28649742, 2017). "Intriguingly, we have also detected cerebellar foliation anomalies in CHARGE syndrome patients, implying a role for CHD7 in GCp development." (PMID 28165338, 2017). "As shown in CHARGE syndrome patients, data from mouse studies confirm that CHD7 is haploidinsufficient for brain development." (PMID 29033785, 2017). "Most CHARGE syndrome patients have brain structural anomalies, implicating an important role of CHD7 during brain development." (PMID 29033785, 2017).
CHARGE syndrome (continued). "There are similarities in the individuals’ facial features and phenotype, including developmental delay, genitourinary abnormalities, and structural brain abnormalities, which exhibits some overlap with CHARGE syndrome (CHD7)." (PMID 28663792, 2017). "Several earlier review articles have comprehensive summarized the developmental roles of CHD7 in multiple organs affected in CHARGE syndrome patients." (PMID 29033785, 2017). "Genetic diagnoses were heterogeneous; the most common diagnoses included Trisomy 21 (n = 18; 12%), 22q11 deletion syndrome (n = 6; 4%) and CHD7 confirmed CHARGE syndrome (n = 5; 4%)." (PMID 28531152, 2017). "The phenotypic similarity between CHARGE syndrome and 22q11.2 deletion syndrome is also apparent in mice with haploinsufficiency of CHD7 and TBX1." (PMID 27957375, 2016). "Because of the regulating function of CHD7, haploinsufficiency of CHD7 affects multiple organ systems, which explains the broad clinical variability seen in CHARGE syndrome." (PMID 26544072, 2015). "The emerging picture from this work suggests that the mechanisms by which CHD7 fine-tunes gene expression are context specific, consistent with the pleiotropic nature of CHARGE syndrome." (PMID 26411921, 2015). "CHD7 encodes a chromatin-remodelling factor (CRF), which implied an epigenetic aetiology for CHARGE syndrome." (PMID 26411921, 2015). "Dominant loss-of-function mutations in the gene encoding chromodomain helicase DNA binding protein 7 (CHD7), which is an ATP-dependent chromatin remodeller, have been identified as the cause of CHARGE syndrome." (PMID 26411921, 2015). "CHARGE syndrome is often classified as a disease arising from maldevelopment of NCCs, known as a neurocristopathy, and CHD7 activity has been shown to have an essential role in the activation of the NCC transcriptional circuitry." (PMID 26102480, 2015). "We report here on a male patient affected by CHARGE syndrome, heterozygous for a deletion involving the promoter region and exon 1 of the CHD7 gene and the contiguous RAB2 gene." (PMID 26334530, 2015). "CHD7 (chromodomain helicase DNA-binding protein 7) is expressed in organs affected by CHARGE syndrome but is widely expressed during fetal development with high levels in epithelial cells of the lung and gut." (PMID 24829898, 2014). "Previous studies on CHD7 suggested that the analysis of this gene should be performed in KS patients having at least two CHARGE syndrome features." (PMID 25254043, 2014). "CHD4 is in the same gene family as CHD7 whose haploinsufficiency leads to CHARGE syndrome, which is a multisystem developmental disorder." (PMID 25329894, 2014). "Further analysis of the Looper strain will facilitate elucidation of the function of Chd7 and the pathology of CHARGE syndrome." (PMID 24840056, 2014). "Mice should have two working copies of the Chd7 gene, and mice that lack one of these suffer from symptoms similar to those of humans with CHARGE syndrome." (PMID 24368733, 2013). "CHD7 is expressed in a wide variety of tissues during development, and CHARGE syndrome phenotypes indicate that it has tissue-specific and developmental stage-specific roles." (PMID 24368735, 2013). "Normal development of these structures has been shown to be dependent on the co-expression of Chd7 and Tbx1 in mice suggesting the likely mechanism by which CHARGE syndrome can lead to a DGS phenotype." (PMID 24198816, 2013). "Mutations in the chromodomain helicase DNA binding protein 7 gene (CHD7) lead to CHARGE syndrome, an autosomal dominant multiple malformation disorder." (PMID 23285124, 2012).
CHARGE syndrome (continued). "These critical roles for Chd7 in retinal and vertebral development were previously unrecognized and our results provide new insights into the role of Chd7 during development and in CHARGE syndrome pathogenesis." (PMID 22363697, 2012). "We then performed a detailed analysis of uncharacterized defects of CHARGE syndrome and show that the presence of Chd7 is crucial for proper neural, retinal and vertebral development in zebrafish." (PMID 22363697, 2012). "Our results support a role for Chd7 in proper CNC migration and differentiation, and substantiate the use of chd7 morphant zebrafish as an in vivo animal model for CHARGE Syndrome." (PMID 22363697, 2012). "Previous studies have demonstrated a role for Chd7 in neuronal development and patients with CHARGE syndrome often display several neurological disorders." (PMID 22363697, 2012). "Similar to the results of adult mouse tissues, Fam124B expression at E12.5 correlated in many embryonic tissues with the Chd7 expression pattern, and therefore Fam124B was found to be expressed in organs affected in CHARGE syndrome." (PMID 23285124, 2012). "Throughout murine development Chd7 is broadly expressed, including organs classically anomalous in CHARGE Syndrome, such as the eyes, heart, and ears." (PMID 21995344, 2011). "We also cannot exclude the possibility that enhancer-activity is dependent on CHD7 at later stages in development, in cell types that are more relevant than ES cells to the phenotype of CHARGE syndrome." (PMID 20657823, 2010). "CHD7, a member of the CHD family, encodes a protein mutated in human CHARGE syndrome, a multiple anomaly disorder that affects hearing, vision, and cardiac, craniofacial, and nervous system development." (PMID 20657659, 2010). "Mice that are homozygous for either nonsense or frameshift mutations in Chd7 (NM_001081417) die around embryonic day 10.5, while heterozygous Chd7 mutants are viable and develop many of the features observed in CHARGE syndrome." (PMID 20657823, 2010). "This study establishes CHD7 as a transcriptional regulator, highlights a novel mechanism of enhancer-mediated regulation, and implies that the multiple anomalies in CHARGE syndrome result from dysregulated expression of tissue-specific genes." (PMID 20657823, 2010). "Heterozygosity for loss of function mutations in CHD7, a human counterpart of KIS-L, leads to CHARGE syndrome, a serious developmental disorder affecting approximately one in 8,500 births." (PMID 18846226, 2008). "In situ hybridization analysis of the CHD7 gene during early human development showed a good correlation between CHD7 expression patterns and the developmental anomalies observed in CHARGE syndrome." (PMID 16959034, 2006). "Due to the presence of two major features of CHARGE syndrome, comparative genomic hybridization analysis and mutation scanning of the entire coding sequence of CHD7 (MIM 608892) was performed, both resulting as negative." (PMID 40004505, 2025). "Disruption of CHD7 confirmed the suspected diagnosis of CHARGE syndrome." (PMID 40692712, 2025). "To test whether CHD7 is essential for neuronal differentiation in iMOPs, we wanted to mimic CHD7 haploinsufficiency in CHARGE syndrome during neuronal differentiation using a knockdown strategy." (PMID 40196636, 2025). "Similarly, CHARGE syndrome, which is often caused by deletions or variants in the CHD-associated gene CHD7, can also result in conotruncal defects." (PMID 38339013, 2024). "Chd7 was broadly expressed during early chick development, consistent with its function as a chromatin remodeller; however, Chd7 transcripts were notably enriched in the developing neural crest in keeping with its known role in CHARGE syndrome." (PMID 39418292, 2024).
CHARGE syndrome (continued). "Leveraging the chd7 mutant zebrafish model to simulate the anesthesia process in patients with CHARGE syndrome can deepen the understanding of the molecular underpinnings of these adverse events, enhancing the safety of anesthetic procedures in this population." (PMID 38892128, 2024). "For CHARGE syndrome, however, individuals who had not undergone CHD7 analysis due to mild symptoms and those with typical CHARGE syndrome but lacking a CHD7 mutation need to be accounted for." (PMID 38790272, 2024). "Interestingly, MTI embryopathy seems to be a clear phenocopy of the CHARGE syndrome (MIM# 214800), a genetic disease related to pathogenic variants in the CHD7 gene." (PMID 39296666, 2024). "While many clinical CHARGE syndrome cases contain pathogenic variants in the CHD7 ORF, it is highly plausible that many of the remaining unattributed cases would be caused by disruptions in cis-regulatory elements controlling CHD7." (PMID 39418292, 2024). "These genes were analysed due to the possibility of isolated CHH occurring in the context of variable expressivity of the syndrome, as in the case of mild variants in CHD7 causing CHH in the absence of other features of CHARGE syndrome." (PMID 39308770, 2024). "Atypical presentations in patients with a CHD7 variant have been reported before, even without or with only one major diagnostic criterion for CHARGE syndrome, according to Verloes." (PMID 38790272, 2024). "CHD7 is associated with CHARGE syndrome and hypogonadotropic hypogonadism-5 with or without anosmia." (PMID 39285472, 2024). "Our findings embed Chd7 in the neural crest gene regulatory network and offer potentially clinically relevant elements for interpreting CHARGE syndrome cases without causative allocation." (PMID 39418292, 2024). "It is worth noting that previous studies of CHD7 have focused on KS, CHARGE syndrome, and myocardial function, whereas our two patients with CHD7 variants did not have olfactory dysfunction or other systemic diseases." (PMID 37679557, 2024). "CHD7 is one of the pathogenic genes associated with coloboma, heart defects, atresia choanae (CHARGE) syndrome, and IHH, while reproductive system dysplasia, the main clinical manifestation of IHH, is only one of the secondary symptoms of CHARGE syndrome." (PMID 37679557, 2024). "CHD7 gene defects are associated with the CHARGE syndrome and hypogonadotropic hypogonadism 5 with or without hyposmia, which are inherited with an autosomal dominant manner." (PMID 37959410, 2023). "CHD7 mutations have also been identified in 5–19% of patients with isolated HH who were not diagnosed with CHARGE syndrome." (PMID 37231428, 2023). "Herein, we present a rare case of patient with CPHD, who despite not fulfilling the diagnostic criteria for CHARGE syndrome, presented with minor characteristics and a CHD7 missense mutation with pathogenic potential." (PMID 37231428, 2023). "Some of the identified variants in the CHD7 gene are associated with a milder clinical picture of CHARGE syndrome, and it cannot be ruled out that in the case of the examined patient the identified variant causes only EVA." (PMID 36833263, 2023). "Those with CHARGE syndrome without CHD7 mutation typically do not have an identified genetic defect." (PMID 35246073, 2022). "While no homozygous embryos were detected beyond E10.5, the heterozygous Chd7 mice recapitulate various symptoms of CHARGE syndrome, such as coloboma, inner ear abnormalities, cleft palate, choanal defects, cardiovascular defects, genital defects, and developmental growth delays." (PMID 36568983, 2022). "In this study, we address the question of why individuals diagnosed with CHARGE syndrome show phenotypic variability by exploring and comparing Chd7 function in two adult mouse models (Chd7+/Whi and Chd7+/tm2a) engineered on different genetic backgrounds to mimic the human condition." (PMID 36232804, 2022).